CDK4 (cyclin dependent kinase 4)
Diseases named in the same sentence as CDK4 in open-access papers (continued):
Sharing a sentence is not in itself a finding about the gene and the disease.
tumor (continued). "Compared with that in normal tissue, CDK4/6 mRNA expression was remarkably higher in tumor tissue overall, which demonstrated that CDK4/6 are abnormally expressed in multiple tumors; however, there was no significant change in some levels between normal tissue and tumor tissue, including CDK6 in OC." (PMID 35095879, 2021). "We aimed to determine whether genomic markers in circulating tumor DNA (ctDNA) can identify patients at higher risk of early progression on fulvestrant therapy with or without palbociclib, a CDK4/6i." (PMID 32940689, 2021). "The CDK4/6 inhibitors have also been proposed in association with chemotherapy agents; in particular, the addition of CDK4/6 inhibitors to gemcitabine exerts a synergistic effect in PDAC cells with increased apoptosis and chemosensitivity, reduction of both invasion and tumor progression." (PMID 34440587, 2021). "Additionally, overexpression of Cyclin D1, a binding partner with CDK4/6, in neuroblasts and low Cyclin D1 expression in ganglioneuroma indicate an involvement of dysregulation of the G1 cell cycle checkpoint in neuroblastic tumor differentiation." (PMID 34069817, 2021). "Interestingly, hematoxylin and eosin (HE) staining of 182R-1 tumors treated for 6 weeks with a vehicle, fulvestrant alone, fulvestrant + CDK4/6i, and triple combination with AKTi showed that tumors treated with vehicle or fulvestrant predominantly consisted of vital tumor cells." (PMID 34433817, 2021). "Therefore, inhibiting CDK4/6 is a potential means to inhibit tumor growth." (PMID 34434893, 2021). "Previously, we reported that Tspan5 is downregulated in gastric cancer tissues and functions as a tumour suppressor in stomach to control the tumour growth by regulation of cell cycle transition from G1‐S phase via decreasing the expression of cyclin D1, CDK4, pRB and E2F1." (PMID 33955149, 2021). "To test whether the observed up-regulation of DNMT1 expression in ALK tumor samples is associated with deregulation of cell cycle–associated genes, we performed Western blot analysis using antibodies against c-MYC, CDK4/CDK6, cyclin D1, and the proliferation marker PCNA." (PMID 33310759, 2021). "Furthermore, our study suggested that the LRRC75A-AS1-hsa-miR-330-5p-CDK4/6 axis might exert its antitumor function by inhibiting the antigen presentation ability of tumor cells and by inhibiting immune cell infiltration and activation." (PMID 35095879, 2021). "Importantly, the triple combination completely blocked tumor regrowth during 8 weeks of treatment, while tumors treated with the standard double combination of fulvestrant and CDK4/6i started to expand after 6 weeks of treatment, suggesting outgrowth of resistant clones." (PMID 34433817, 2021). "In addition to TGF-β1, TGF-β2 has been shown to specifically activate MAPK/p38α/β signaling in the bone marrow that causes induction of DEC2/SHARP1 and p27, and the downregulation of cyclin-dependent kinase 4 (CDK4) and results in the dormancy of malignant disseminated tumor cells (DTCs)." (PMID 33925575, 2021). "Additionally, hyperactivation of Cyclin D/Cdk4 could help (early) tumor cells deal with ongoing replication stress that is frequently observed in cancer cells." (PMID 33806417, 2021). "Indeed, the coadministration of MDM2 inhibitors and CDK4/6 inhibitors leads to tumor regression." (PMID 34071228, 2021). "In addition, cell cycle-targeting drugs CDK4/6 inhibitor may enhance the expression of PD-L1 on tumor cells, indicating the significance of combining ICBs." (PMID 34150632, 2021). "Moreover, the associations of CDK4/6 with the tumor immune microenvironment in OC have not been determined." (PMID 35095879, 2021). "Importantly, this pathway can be targeted via MDM2 to activate tumour suppressive outcomes that may be able to bypass diverse mechanisms of resistance to CDK4/6i altogether." (PMID 34804982, 2021).
tumor (continued). "Additionally, when tumor cells were treated with single-agent MEK or CDK4 inhibitor, there was a reciprocal activation of the CDK4 or MEK signaling pathways, respectively, showing a dynamic switching of signaling pathway activation and survival dependencies in the face of pharmacological treatments." (PMID 34309585, 2021). "Note that many different mechanisms can lead to acquired resistance to CDK4/6 inhibitors, including cyclin D–CDK4/6–Rb activation, the activation of other proliferation pathways, the alteration of the tumor microenvironment, and the adjustment of the tumor metabolism." (PMID 34830174, 2021). "The CDK4-specific effect of palbociclib on displacing p21 from cyclin D1-CDK4-p21—but not from cyclin D1-CDK6-p21—suggests that the relative ratio of CDK4 to CDK6 within a tumor may dictate drug sensitivity and resistance." (PMID 34099663, 2021). "Upon disease progression, we used a targeted systemic approach based on the whole genomic profile of the primary tumor, which showed PTEN loss, which is predictive of a benefit from an mTOR inhibitor, and a CCND1 amplification, which predicts sensitivity to CDK4/6 inhibitors." (PMID 34829431, 2021). "Also, the faster progression and shorter survival of Hgf-Cdk4R24C mice compared to Cdk4R24C with OH-BBN induced urothelial tumors indicates that the co-occurrence of both Hgf overexpression and overactivation of Cdk4 (R24C) led to a more progressive tumor phenotype." (PMID 34232958, 2021). "However, although CM has a much higher CDKN2A loss than MM, MM tends to show a greater frequency of CCND1 and CDK4 amplification, implying CDK4 blocking agents may achieve a desired anti-tumor effect on MM." (PMID 34350118, 2021). "Tumors treated with combined CDK4/6i and fulvestrant were smaller and contained infiltrating fat cells that were more pronounced in tumors treated with the triple combination wherein only smaller tumor islets containing central degeneration surrounded by fat tissue were observed." (PMID 34433817, 2021). "In addition, the current results show that AK2 can specifically bind to rhCDK4 and endogenous CDK4 in tumour cells, which indicates that AK2, as a single-chain antibody, maintains its unique biological structure and biological activity in this soluble expression and purification system." (PMID 34930213, 2021). "Thus, therapies directed to Cyclin D1/CDK4 may be useful in targeting both the tumor cell and modulating the activity of a stromal cell type that is critical to support malignant progression." (PMID 33317149, 2020). "In addition, a co-expression was found between ASPM and CDK4 in human tumor tissues." (PMID 32742488, 2020). "Similarly, CDK4 over-expression promoted the evolution of tumor cell cycle." (PMID 32796813, 2020). "Importantly, tumor cells have numerous mechanisms of resistance to CDK4/6 inhibitors at their disposal, which are both cell cycle specific (e.g., CCNE amplification and CDK2 hyperactivation) and independent of the cell cycle (e.g., activation of PI3K/AKT/mTOR signaling)." (PMID 32344731, 2020). "Tumour sections stained with Ki67 and pRb revealed a significant reduction of both Ki67-positive cells and pRb-positive cells in tumours following intrapulmonary administration of P2shortA combined with Abemaciclib, indicative of a reduced proliferative index and reduced CDK4 activity, respectively." (PMID 32104498, 2020). "Either CDK4/6 or mTOR inhibitors increase PD-L1 protein levels by disruption of CDK4/6/cullin3SPOP or mTORC1/p70S6K/β-TrCP pathway-mediated PD-L1 ubiquitination and degradation, while the combination of CDK4/6 inhibitors with PD-L1/PD-1 blockade effectively enhances tumor immunotherapy." (PMID 33159034, 2020). "CDK4/6 inhibitors may be more effective when combined with other signaling pathway inhibitors, which is consistent with the complexity and intersectionality of tumor signaling pathway interactions." (PMID 32357912, 2020).
tumor (continued). "Furthermore, CDK4/6 inhibitors promote tumor cell clearance by enhancing cytotoxic T cells (CTLs)." (PMID 32357912, 2020). "The study of phenotypic changes occurring in these tumor cells during and after HER2-blocking therapy showed a switch to a low-proliferative luminal A phenotype, more evident in HR+ than in HR- tumors, associated with an increased sensitivity to CDK4/6 inhibitors." (PMID 32210163, 2020). "Furthermore, studies have shown that CDK4/6 inhibitors may increase tumor immunogenicity, which provides a rationale for combination regimens composed of CDK4/6 inhibitors and immunotherapies." (PMID 33364954, 2020). "Interestingly, preclinical studies showed that CDK4/6 inhibitors could also regulate mitogenic kinase signaling, inducing senescence and promoting anti-tumor immunity, providing the rationale of combinations with immunotherapy agents." (PMID 32899866, 2020). "CDK4/6 inhibitors could repress immunosuppressive regulatory T cells (Tregs) and enhance effector T cells response by upregulating the level of cytokines (IL-2) in the tumor microenvironment." (PMID 32899866, 2020). "In addition we validated the knockdown of CDK4 and 6 in our tumor sections." (PMID 30858922, 2019). "Addition of the CDK4/6 inhibitor LEE011 to BYL719 caused a simultaneous reduction of p-RB and p-S6, and a more complete inhibition of p-S6, leading to decreased expression of the pro-survival protein MCL-1, an induction of apoptosis, and an enhanced reduction of tumor growth in a PDX model of TNBC." (PMID 31101835, 2019). "Based on where each of these two classes of drugs works during the cell cycle, we hypothesize that two potential dosing schedules may produce enhanced cell killing effects: 1) initial exposure of cycling tumor cells to a CDK4/6 inhibitor synchronizes cells at the G1 phase." (PMID 31600301, 2019). "In addition to loss of large regions on chr1p, 3p, and 11q and a broad gain of chr17q, VCF2CNA found frequent focal amplifications of MYCN in NBL tumors and several potential cancer-related CNAs, including high-level amplifications of CDK4 (1 tumor), and ALK (2 tumors)." (PMID 31316100, 2019). "With CDK4/6 inhibitors being an integral component in the treatment of metastatic breast cancer, it has become increasingly important to understand the impact of these inhibitors on the molecular characteristics of the tumor and, subsequently, second- and third-line treatment options." (PMID 31852484, 2019). "Thus, it is possible that MELK represents a surrogate marker of E2F1 activation in this tumor type and might be helpful to select people to be treated with CDK4/6 inhibitors." (PMID 31861475, 2019). "In addition to a mutation, deletion or epigenetic silencing of the RB gene, the RB tumor suppressive pathway can be circumvented by overexpression of cyclin D, Cyclin D which along with its binding partners CDK4/6 hyperphosphorylates RB, thus disabling its tumor suppressive activity." (PMID 30349650, 2018). "Indeed, several chemotherapeutic drugs and radiation are known to be able to induce senescence in tumor cells, including inhibitors of CDK4, aurora kinase B (AURKB), casein kinase 2 (CK2), and sunitinib, a known multi-targeted receptor tyrosine kinase inhibitor." (PMID 30687637, 2018). "Also known as multiple tumor suppressor (MTS1), it can inhibit the activity of cyclin-dependent kinase 4 (CDK4) or CDK6, which thereby inhibit cell cycle and cause G1 retardation of cells, thus inhibiting tumor cell proliferation and facilitating tumor cell apoptosis." (PMID 29299129, 2017). "Therefore, we investigated whether the combined expression of selected genes could be used to build a surrogate marker to predict the CDK4 modification profile of a tumor." (PMID 28566333, 2017).
tumor (continued). "We found that the concentrations of G1T38 in tumors closely correlated with inhibition of tumor pRB, demonstrating that G1T38 in the tumor could inhibit the CDK4/6/RB pathway and sustain tumor cell growth inhibition after G1T38 plasma concentrations were <1 ng/ml." (PMID 28418845, 2017). "In addition, APS inhibit the tumor cell growth in Kunming mice with Ehrlich's ascites carcinoma, decrease Bcl-2 and CDK4 levels, increase the percentage of CD3+ and CD4+ T-lymphocytes, the ratio of CD4+/CD8+ T cells and the expression of IL-2/IL-2R in spleen and Bax in tumor tissue." (PMID 29344421, 2017). "Furthermore, the genes encoding CDK4 and CDK6 are amplified in a subset of human neoplasms." (PMID 28418845, 2017). "Interestingly, we also found these effects to be CDK4-specific and CDK6-independent, indicating that specific CDK4 pharmacological inhibitors, may prove efficient drugs for eliminating BCSCs and further preventing tumor recurrence in human TNBCs." (PMID 27759034, 2016). "However, we observed different tumor behavior in response to the CDK4 inhibitor." (PMID 26528855, 2015). "In response to mitogenic growth factors, the CDK4/6 kinase together with one of three D-type cyclins (D1, D2, D3) initiates G1 progression by virtue of its capacity to phosphorylate the retinoblastoma protein (RB), a bona fide tumor suppressor and Gate Keeper of cell division." (PMID 26697514, 2015). "Therefore, it is possible that the water decoction of Taxus cuspidate which may inhibit expression of these cyclin D1 and CDK4 to suppress the tumor growth." (PMID 24719642, 2014). "In contrast, increasing cdk4 dramatically increased these transcript levels, especially those encoding AKR1C3, an enzyme that converts estrone to 17β-estradiol, a change that could result in a pro-estrogenic state favoring tumor growth." (PMID 24848372, 2014). "Tumor inhibition may thus be induced by down-regulation of positive cell cycle regulators, such as cyclin D1, D2 and CDK4, along with up-regulation of the negative regulator, cyclin dependent kinase inhibitor, p27, and its subsequent inhibition of Rb phosphorylation and G1 arrest." (PMID 24040358, 2013). "CCND1 downregulation is well characterized to decrease activation of cyclin-dependent kinases Cdk4 and Cdk6, that are not only required for G1 to S phase transition during cell cycle progression but also are major players in interaction with stromal cells that sustain tumor growth." (PMID 24143218, 2013). "However, forced stimulation of CDK4 causes sequestration of p21 in cell lines, increasing the risk of becoming OSCC, on the other hand the application of recombinant p21 in OSCC xenografts, has shown to cause delay in vivo tumor growth." (PMID 23385498, 2013). "In this regard, and to further support our hypothesis that radiolabeled Cdk4 inhibitors are suitable radiotracers for tumor imaging, comprehensive in vivo experiments of [124I]CKIA and [124I]CKIB involving biodistribution and small animal PET studies should be performed." (PMID 19551155, 2009). "We hypothesized that potent Cdk4 inhibitors, which are suitable for cancer therapy, are also of interest as radiotracers for imaging of cell proliferation processes in vivo and especially for tumor visualization by positron emission tomography (PET)." (PMID 19551155, 2009). "Multiple gene amplifications, including c-Myc, were observed in head and neck SCC and the over-expression of the cyclin-dependent Kinase 4 (Cdk4) either by gene amplification or through the c-Myc regulated pathway may also play a key role in the progression of these tumours." (PMID 22275997, 2009). "This study illustrates that single and combined administrations of PI3K, FGFR, CDK4/6, and AKT inhibitors in a NES/tNES model have dose-dependent and additive/synergistic anti-MB activity impacting tumor growth." (PMID 41734992, 2026).
tumor (continued). "Here we provide a schematic overview on their contribution in tumor progression, since CDK4 and CDK6 have distinct and overlapping functions in tumor development, affecting stemness, angiogenesis, transcription, metabolism, and immune modulation." (PMID 39800748, 2025). "Only those molecules that (i) demonstrated selective cytotoxicity (SI > 2 in at least one tumor cell line) and (ii) showed strong molecular docking affinity toward VEGFR2 and/or CDK4 were advanced to redox-related assays." (PMID 41471388, 2025). "These exciting findings reveal how existing clinical therapeutics, like inhibitors of CDK4/6 and MEK, can be repurposed to sensitize tumors to ICB immunotherapy and provide durable tumor control." (PMID 40723291, 2025). "However, optimal therapy after tumor progression to ET plus CDK4/6i remains unclear." (PMID 39982725, 2025). "Patient OS#2 displayed a combined gain in CDK4 and CCND3 genes, and this CNV profile was present in both samples, primary tumor and recurrence, from the same patient." (PMID 41514647, 2025). "The combination of CDK4/6 inhibitors with anti-HER2 therapy showed potential as a promising approach for HR-positive, HER2-positive patients by significantly reducing tumor cell viability and promoting apoptosis in preclinical models." (PMID 40687942, 2025). "Inhibition of the activity of the aromatase enzyme, cyclin D1, CDK4, Bcl-xL, and pS2, while increasing the expression of CCAAT/C/EBP, pERK-1&-2, and p57Kip2 that results in decrease the tumour growth." (PMID 40427522, 2025). "Targeted agents (CDK4/6, PARP inhibitors) can concurrently impair tumor cells and foster a more permissive immune microenvironment." (PMID 41567982, 2025). "Consistently, a combination of XPO1 inhibitor KPT‐330 and CDK4/6 inhibitor Palbociclib effectively inhibited BLBC cell proliferation and tumor growth." (PMID 39888288, 2025). "Our analysis of non-tumor cells, such as T cells, NK cells, and B cells, also identified TFF3 as a consistent predictive biomarker for favorable outcomes with CDK4/6is." (PMID 39955556, 2025). "Ongoing research efforts are focusing on understanding the role of tumor type, co-existing genomic alterations, and aberrant activation of CDK2 as potential biomarkers of response and resistance to CDK4/6 inhibition." (PMID 40317086, 2025). "Y5-3 features a disulphide (-S-S-) bond extended from the ALK-targeting PROTAC linker, conjugated to palbociclib (a CDK4/6 inhibitor), and cleaved by GSH to selectively release its functional moieties in tumour cells." (PMID 40793752, 2025). "As such, CDK4 and CDK6 are frequently overexpressed or aberrantly activated by overexpression of Cyclin D and subsequently promote tumor cell proliferation in various types of cancer, such as colon, breast, and lung cancers." (PMID 41154395, 2025). "Among them, cyclin-dependent kinase 4/6 (CDK4/6) exhibits abnormal activation during tumorigenesis and tumor development." (PMID 40083693, 2025). "Mechanistically, CDK4/6 directly binds to and phosphorylates DUB3, which leads to the deubiquitination and stabilization of YAP1, thereby promoting tumor growth and chemo-resistance of HCC." (PMID 40307228, 2025). "Several cell cycle proteins, including D- and E-type cyclins, CDKs (CDK2, CDK4, CDK6), PLK1, and Aurora kinases, are commonly overexpressed in cancers and contribute to tumor development and progression." (PMID 41154590, 2025). "Most importantly, the combination of two clinical drugs (CDK4/6 inhibitor Palbociclib and XPO1 inhibitor KPT‐330) effectively inhibited BLBC cell proliferation and tumor growth." (PMID 39888288, 2025). "Fourth, KIFC2 exerted its tumor-promoting and therapy-resistant functions in HR+/HER2– BC by recruiting USP9X to stabilize CDK4." (PMID 40299549, 2025). "The CDK-cyclin complexes, particularly CDK4 and CDK6 with D-type cyclins, regulate the cell cycle by phosphorylating the retinoblastoma family of proteins Rb, p107, and p130, which act like tumor suppressors." (PMID 40149342, 2025).